TRPC2 (transient receptor potential cation channel subfamily C member 2 (pseudogene))
Synonyms: TRPC2P
Gene: Transcribed unitary pseudogene on chromosome 11 (3,616,679 to 3,637,549, forward strand). Ensembl gene ENSG00000182048.
Diseases named in the same sentence as TRPC2 in open-access papers:
TRPC2 is named in the same sentence as 1 disease in open-access papers, as found by Europe PMC text mining. Sharing a sentence is not in itself a finding about the gene and the disease. The quoted sentences say what the papers report.
breast carcinoma (1 paper, 2025). "In contrast, the role of TRPC1 in breast cancer metastasis is inconsistent with TRPC2." (PMID 40078961, 2025). "TRPC channels have not been well studied in breast cancer metastasis, and TRPC2 silencing reduced detectable breast cancer lung metastases in a 4T1 mouse model of homozygous metastatic breast cancer." (PMID 40078961, 2025).